CYLD (CYLD lysine 63 deubiquitinase)
Diseases named in the same sentence as CYLD in open-access papers (continued):
Sharing a sentence is not in itself a finding about the gene and the disease.
salivary gland neoplasm (2 papers, 2016 to 2020). Tumors of the SALIVARY GLANDS. "CYLD mutations also characterize a subset of salivary gland neoplasms: both basal cell salivary adenomas and adenocarcinomas can possess CYLD mutations." (PMID 32461623, 2020).
Stroke (2 papers, 2017 to 2025). Sudden impairment of blood flow to a part of the brain due to occlusion or rupture of an artery to the brain. "As a negative regulator of the NF-κB pathway, CYLD plays a central role in inflammatory conditions such as neuronal death following stroke." (PMID 39945824, 2025). "In another stroke model (transient middle cerebral artery occlusion followed by reperfusion), SPATA2 was identified as a partner protein of CYLD, contributing to its recruitment." (PMID 39945824, 2025).
abdominal aortic aneurysm (1 paper, 2023). Enlargement and ballooning of the vessel that supplies arterial blood to the abdomen, pelvis and legs. "CYLD promotes the transdifferentiation of AFs by directly binding to Nox4 through the USP structural domain, which plays a role in vascular remodeling, and CYLD can be used as a new target for vascular anti-inflammatory therapy for diseases such as abdominal aortic aneurysms." (PMID 37176077, 2023).
Arthritis (1 paper, 2024). Inflammation of a joint. "In this study, we pursued το decouple the CYLD involvement in the inflammatory behavior of SFs, by employing both acute and chronic TNF-dependent modeled arthritis, coupled with genetic targeting and biochemical studies on DUB-deficient Cyld SFs." (PMID 39122678, 2024).
autism (1 paper, 2023). Persistent deficits in social interaction and communication and interaction as well as a markedly restricted repertoire of activity and interest as well as repetitive patterns of behavior. "Beyond skin, the CYLD variant-related neurodegenerative phenotype seen in humans has prompted a new direction of investigation, with animal modelling already suggesting an important role for CYLD in unexpected phenotypes such as autism-like behaviours." (PMID 37387450, 2023).
autoimmune disease (1 paper, 2023). A disorder resulting from loss of function or tissue destruction of an organ or multiple organs, arising from humoral or cellular immune responses of the individual to their own tissue constituents. "Unlike A20 and CYLD, associations between polymorphisms in the Cezanne gene and autoimmune diseases are not well documented." (PMID 37893484, 2023).
bladder tumor (1 paper, 2016). "For this purpose, 10 bladder tumor specimens were freshly collected during radical cystectomy, and the nucleus or total proteins were extracted separately to examine the expression of NF-κB subunits or CYLD." (PMID 27391066, 2016).
cardiopulmonary diseases (1 paper, 2020). "Combining murine and human results, we suggest that CYLD may represent a novel target gene for PH and cardiopulmonary diseases." (PMID 33330645, 2020).
Cerebral ischemia (1 paper, 2017). Restriction of arterial blood supply to the brain associated with insufficient oxygenation to support the metabolic requirements of the tissue. "Also, EA inhibited the p38 MAPK signaling pathway in the hippocampus of rats with cerebral ischemia/reperfusion injury and EA reduces CYLD protein at 6 h reperfusion, which may be associated with p38 MAPK signaling." (PMID 29163038, 2017). "We speculated that the location of CYLD is associated with cell status and NF-κB expression was observed in cortical neurons after cerebral ischemia, suggesting an anti-inflammatory role for CYLD." (PMID 29163038, 2017). "Moreover, we explored the role of CYLD in regulating interactions between neurons and microglia in neuro-inflammation induced by focal cerebral ischemia/reperfusion." (PMID 29163038, 2017). "Thus, we explored temporal and spatial expression of cylindromatosis (CYLD), a negative feedback inhibitor of the NF-κB signaling pathway, to learn whether CYLD is essential for EA and reduction of inflammatory injury after focal cerebral ischemia/reperfusion." (PMID 29163038, 2017). "Thus, CYLD immunopositive neurons may be key to reducing inflammatory injury after focal cerebral ischemia/reperfusion in rats." (PMID 29163038, 2017).
chronic hepatitis C (1 paper, 2014). "A reduced copy number of the CYLD gene was observed in more than 30% of human HCCs caused by chronic hepatitis C." (PMID 25329885, 2014).
chronic lymphoid leukemia (1 paper, 2024). "Abnormal splicing of the tumor suppressor CYLD activates the NF-κB pathway, thereby boosting the development of chronic lymphoid leukemia." (PMID 38690287, 2024).
Crohn disease (1 paper, 2022). A gastrointestinal disorder characterized by chronic inflammation involving all layers of the intestinal wall, noncaseating granulomas affecting the intestinal wall and regional lymph nodes, and transmural fibrosis. "For instance, CYLDex7/8 expression and activity has been primarily described in immune cells, and Tang and colleagues reported increased CYLD splicing in the T cells of Crohn’s Disease patients." (PMID 36531014, 2022).
cutaneous papillomas (1 paper, 2020). "In mouse models, inactivation of CYLD in the epidermis promotes sebaceous hyperplasia and proliferations with basaloid and sebaceous components, while global knockout mice are prone to developing cutaneous papillomas." (PMID 32461623, 2020).
dermatomyositis (1 paper, 2019). Dermatomyositis (DM) is a type of idiopathic inflammatory myopathy characterized by evocative skin lesions and symmetrical proximal muscle weakness. "In contrast, CYLD was expressed diffusely in the sarcoplasm of atrophied myofibres in patients with dermatomyositis." (PMID 31406156, 2019).
diabetic nephropathy (1 paper, 2021). "Furthermore, the regulation of NF-κB signaling by CYLD has also been demonstrated to be important in preventing inflammation leading to diabetic nephropathy, adding to the therapeutic potential of CYLD." (PMID 34391779, 2021).
eczema (1 paper, 2025). "CYLD expression appeared particularly strong in the lesional skin of a patient with clinical signs of superinfected eczema (patient AD3)." (PMID 39958342, 2025).
epilepsy (1 paper, 2024). A brain disorder characterized by episodes of abnormally increased neuronal discharge resulting in transient episodes of sensory or motor neurological dysfunction, or psychic dysfunction. "Currently, a multitude of studies have explored autophagy-related genes, such as WDR45, CYLD, and 4E-BP2, which have been linked with epilepsy development." (PMID 40217519, 2024).
experimental autoimmune encephalomyelitis (1 paper, 2024). An autoimmune demyelinating disease of the central nervous system that is produced experimentally in animals by the injection of homogenized brain or spinal cord in Freund's adjuvant. "Additionally, CYLD overexpression did not modify the microglial response to LPS-induced neuroinflammation or the disease severity in experimental autoimmune encephalomyelitis (EAE)." (PMID 39302418, 2024). "Additionally, constitutive CYLD expression in microglia did not affect CNS immune cell infiltration either in the steady state or in experimental autoimmune encephalomyelitis (EAE), a mouse model for Multiple Sclerosis (MS)." (PMID 39302418, 2024).
fibrosarcoma (1 paper, 2022). A malignant mesenchymal fibroblastic neoplasm affecting the soft tissue and bone. "For example, it has been reported that RIP1 is deubiquitinated by both A20 and CYLD in mouse fibrosarcoma cells, but inhibition of CYLD protects cells from necroptosis, while A20 depletion can sensitize cells to death by necroptosis." (PMID 37420422, 2022).
glaucoma (1 paper, 2011). Increased pressure in the eyeball due to obstruction of the outflow of aqueous humor. "Our results show that a glaucoma-associated mutant of optineurin, H486R, is altered in its interaction with CYLD." (PMID 21408173, 2011). "Wild-type optineurin or its glaucoma-associated mutants (E50K, H486R and R545Q) were co-transformed with CYLD in yeast." (PMID 21408173, 2011). "A glaucoma-associated mutant of optineurin (H486R) shows reduced binding to CYLD." (PMID 21408173, 2011). "We tested the hypothesis that some of the glaucoma-associated mutants of optineurin may be altered in their interaction with CYLD." (PMID 21408173, 2011). "One of the glaucoma-associated mutants, H486R, failed to interact with CYLD." (PMID 21408173, 2011).
glomerulonephritis (1 paper, 2023). A renal disorder characterized by damage in the glomeruli. "CYLD, encoding a deubiquitinase, appears to be overexpressed in kidney samples from patients with SLE glomerulonephritis." (PMID 36768581, 2023).
Hepatic steatosis (1 paper, 2022). Steatosis is a term used to denote lipid accumulation within hepatocytes. "CSN-associated DUBs USP15 and USP48 contribute to NF-κB regulation and cylindromatosis (CYLD) is involved in hepatic steatosis." (PMID 35066747, 2022).
hyperhomocysteinemia (1 paper, 2021). A serious metabolic condition caused by mutations in the MTHFR gene, medications, or nutritional deficiency. "For the underlying mechanism of transition process, previous studies have revealed the roles of TGFβ, hypoxia, angiotension II, endothelin-1, IL-6, hyperhomocysteinemia (HHcy), cylindromatosis (CYLD), nicotinamide adenine dinucleotide phosphate (NADPH) oxidase 4 (Nox4), and Fizzl." (PMID 34901214, 2021).
injury (1 paper, 2017). Damage inflicted on the body as the direct or indirect result of an external force, with or without disruption of structural continuity. "Mutation or disruption of the activity of CYLD in animals aggravates acute and chronic liver injury." (PMID 29163038, 2017).
intestinal tumour (1 paper, 2016). "To assess the role of epithelial CYLD in DNA damage-driven tumorigenesis, we exposed CYLDΔ932IEC mice to a model of inflammation-independent intestinal tumour development induced by repeated injections of AOM." (PMID 27561390, 2016).
intrahepatic cholestasis (1 paper, 2023). A cholestasis characterized by impairment of the bile flow caused by obstruction located in the liver. "Polymorphic variants of CYLD, GC, MBL2, and ZNF572 genes have been collectively associated with the risk of preterm birth or recurrent late pregnancy loss, while dysregulated expression of CYP8B1 may be responsible for pregnancy intrahepatic cholestasis in mice." (PMID 36768581, 2023).
invasive breast carcinoma (1 paper, 2020). A carcinoma that infiltrates the breast parenchyma. "Overall, our study provides compelling evidence that could explain the association of CYLD downregulation at least with a subset of poor-prognosis invasive breast cancers and identify valuable elements of a growth regulatory framework that can be exploited for therapeutic and diagnostic purposes." (PMID 32722292, 2020).
kidney injury (1 paper, 2021). Trauma to the kidney. "An IKK inhibitor could reduce the phosphorylation of CYLD and inhibit the ubiquitination of Nrf2 to improve oxidative stress-induced kidney injury in ORN." (PMID 34711178, 2021).
leukoplakia (1 paper, 2021). A white patch or plaque on a mucous membrane that cannot be characterized clinically or pathologically as any other disease. "In addition, CYLD, CARD11, TCF7, CCR7, KLRB1, CD28, and ICOS were other significantly highly expressed genes among the proliferative leukoplakia subgroup (log2 fold changes, 0.65–3.51; all Padj = 0.001)." (PMID 36860910, 2021).
listeriosis (1 paper, 2013). A bacterial infection caused by Listeria monocytogenes. "In conclusion, these findings identify CYLD as a potential therapeutic target in severe listeriosis." (PMID 23825949, 2013). "Importantly, in these experimental models inhibition of NF-κB by CYLD was protective, which is in marked contrast to our study in listeriosis." (PMID 23825949, 2013). "Here, we investigated whether the deubiquitinating enzyme CYLD, which is an inhibitor of NF-κB-dependent immune responses, regulated these protective host responses in murine listeriosis." (PMID 23825949, 2013). "In vivo, CYLD also reduced hepatic STAT3 K63-ubiquitination and activation, NF-κB activation, IL-6 and NOX2 mRNA production as well as fibrin production in murine listeriosis." (PMID 23825949, 2013). "Overall, α-IL6, STAT3 siRNA, and warfarin treatment further illustrated that CYLD impaired IL-6/STAT3-induced fibrin production resulting in impaired pathogen control and death from severe listeriosis." (PMID 23825949, 2013). "In addition, CYLD reduced K63-ubiquitination and phosphorylation of STAT3 resulting in an impaired IL-6/STAT3-dependent production of fibrin by hepatocytes as well as fibrin deposition in the liver, which are also important for protection in listeriosis." (PMID 23825949, 2013).
lymphadenitis (1 paper, 2021). Acute or chronic inflammation of one or more lymph nodes. "But there were significant difference in phospho-BTK and phospho-CYLD in the non-GCB-DLBCL patient samples (P1–P5) compared with the lymphadenitis patient samples (B1–B5)." (PMID 33827598, 2021).
Lymphadenopathy (1 paper, 2014). Enlargement (swelling) of a lymph node. "The expression of CYLD must be tightly regulated since overexpression of the short spliced variant of CYLD gene (sCYLD) resulted in splenomegaly and lymphadenopathy, hyperactivation of CD4+ T cells and decrease in mTECs." (PMID 24917867, 2014).
lymphoblastic B-cell leukemia (1 paper, 2023). "Recently, mutations in CYLD gene are associated with the susceptibility to pediatric lymphoblastic B-cell leukemia, although this gene alterations involved in AML is not fully understood." (PMID 37549179, 2023).
malaria (1 paper, 2017). Malaria is a serious and sometimes fatal disease caused by a parasite that commonly infects a certain type of mosquito which feeds on humans. "In this study, we addressed the role of CYLD in primary Plasmodium infections and can exclude a critical role in pre-erythrocytic parasite development and life cycle progression to blood infection, the only parasite stage that causes malaria." (PMID 28203236, 2017). "Together, we were able to show that host deubiqutinating enzymes play an important role in ECM and that CYLD promotes ECM supporting it as a potential therapeutic target for adjunct therapy to prevent cerebral complications of severe malaria." (PMID 28203236, 2017). "Since CD4+ T cells also play an important role in the control of blood-stage malaria, we determined the influence of CYLD on the CD4+ T cell numbers in the blood and brain during ECM." (PMID 28203236, 2017). "Our data indicate that CYLD inhibition might also be an attractive therapeutic option in severe malaria in combination with antiparasitic drugs." (PMID 28203236, 2017). "Since the role of host deubiquitinating enzymes (DUBs) in malaria is yet unknown, we investigated how the DUB cylindromatosis (CYLD), an important inhibitor of several cellular signaling pathways, influences the outcome of ECM." (PMID 28203236, 2017).
metastatic cancer (1 paper, 2022). A carcinoma which has spread from the original site of growth to another anatomic site. "We identified genes with a mean CCF more than two standard deviations from the mean per cancer type, and here we found that CYLD had a CCF significantly below average, indicating that it is more subclonal, in metastatic cancer in 6 cancer types (BLCA, BRCA, COAD, LUNG, PRAD and SKCM)." (PMID 36497297, 2022).
metastatic tumours (1 paper, 2022). "When we further explored the frequency and timing of CYLD mutations, we found that there were only 12 timed driver mutations of CYLD across all primary cancers (4 early, 8 late), whereas there were 98 across metastatic tumours (6 early, 92 late)." (PMID 36497297, 2022). "The most commonly subclonal gene found in metastatic tumours was CYLD, found in 6 different cancer types (BLCA, BRCA, COAD, LUNG, PRAD and SKCM)." (PMID 36497297, 2022).
middle ear cholesteatoma (1 paper, 2010). "We also examined the relationship between CYLD expression and NF-κB activation in middle ear cholesteatoma." (PMID 20414373, 2010).
middle ear infection (1 paper, 2015). "In infectious diseases, CYLD has a disease-specific effect and CYLD-deficient mice suffer from exacerbated Escherichia coli pneumonia and Haemophilus influenzae middle ear infection but are protected against lethal Streptococcus pneumoniae and Lm infection." (PMID 26834734, 2015).
muscular atrophy (1 paper, 2019). The loss of muscle tissue due to inactivity or disease. "CYLD expression was diffuse in the sarcoplasm of grouped atrophic muscle fibres from patients with progressive muscular atrophy." (PMID 31406156, 2019).
non-melanoma skin carcinoma (1 paper, 2021). "Later, it was also shown that the expression of functionally inactive mutated forms of CYLD promoted tumor development and progression of non-melanoma skin cancer (NMSC)." (PMID 34201751, 2021).
Obesity (1 paper, 2021). Accumulation of substantial excess body fat. "In this study, we observed that IKK promoted renal injury caused by obesity through CYLD phosphorylation and that an IKK inhibitor could alleviate lipid deposition and oxidative stress injury in ORN, which may provide a feasible target for the treatment of kidney damage caused by ORN." (PMID 34711178, 2021). "Therefore, we hypothesized that IKK promoted oxidative stress injury caused by obesity by stimulating CYLD phosphorylation." (PMID 34711178, 2021).
open-angle glaucoma (1 paper, 2015). Chronic outflow obstruction of the eye's drainage canals that can lead to increased internal eye pressure and optic nerve damage. "In the light of the close relationship between CYLD and apoptosis, it could be speculated that the deregulation of the Optn/TBK1/CYLD axis could be involved in the neuronal cell death observed in Open Angle Glaucoma and familial ALS, independently of its effect on the antiviral immune pathway." (PMID 25923723, 2015).
oral cancers (1 paper, 2025). "As described by Shigeishi (2023), in HPV-positive oral cancers, mutations in the PIK3CA gene are frequently observed, while there are somatic mutations in ZNF750, FGFR3, DDX3X, CASZ1, PTEN, and CYLD, differentiating them from HPV-negative oral cancers." (PMID 40284955, 2025).
oropharyngeal squamous cell carcinoma (1 paper, 2022). "We previously reported that TRAF3 and CYLD alterations in a subset of HPV+ oropharyngeal squamous cell carcinoma (OPSCC) tumors correlated with NF-κB activation and improved survival." (PMID 35634245, 2022).
papillary thyroid cancer (1 paper, 2017). "A study published in 2014 found down-regulation of miR-181b and noted a link between microRNA down-regulation and apoptosis through targeting the CYLD gene, however, the study was done in a human papillary thyroid cancer cell line which may not adequately represent the in vivo situation." (PMID 28031538, 2017).
papilloma (1 paper, 2016). A benign epithelial neoplasm that projects above the surrounding epithelial surface and consists of villous or arborescent outgrowths of fibrovascular stroma. "Further, the average tumor size of papilloma developed in the CYLD−/− mice were >2.8 times of those found in the CYLD+/+ mice, implicating a potential CYLD gene dose effect on tumor cell proliferation." (PMID 31093340, 2016).
retinal degeneration (1 paper, 2024). Degeneration of the retina. "Microscopic analysis of the ocular fundus revealed that CYLD knockdown in the RPE resulted in retinal degeneration, marked by notable thinning of the retina." (PMID 39373352, 2024). "Overall, the disruption of this regulatory mechanism due to CYLD deficiency damages the microvilli of RPE cells, suppresses the phagocytosis of POS, and ultimately contributes to retinal degeneration." (PMID 39373352, 2024). "CYLD deficiency in aged mice led to impaired RPE phagocytic function and retinal degeneration." (PMID 39373352, 2024).